PPP1R42 (protein phosphatase 1 regulatory subunit 42)
Description:
Regulates phosphatase activity of protein phosphatase 1 (PP1) complexes in the testis.
Synonyms: LRRC67; dtr; TLLR; TLRR
Tractability: PROTAC: ubiquitination databases record sites on it.
Gene: Protein-coding gene on chromosome 8 (66,964,099 to 67,056,604, reverse strand). Ensembl gene ENSG00000178125.
Subcellular location: Cytoplasm, cytoskeleton; Cytoplasm, cytoskeleton, microtubule organizing center, centrosome
Gene Ontology:
Molecular function: actin binding; dynein complex binding; tubulin binding
Cellular component: centrosome; manchette; microtubule cytoskeleton; microtubule organizing center; cytoskeleton
Genetic constraint (gnomAD): Loss-of-function variants: 6 observed, 6.89 expected, observed/expected ratio (o/e) 0.87, 90% interval 0.47 to 1.65. That is too few expected variants to judge how well the gene tolerates losing a copy. Missense variants: 64 observed, 67.85 expected, observed/expected ratio (o/e) 0.94, 90% interval 0.77 to 1.16. Synonymous variants: 26 observed, 26.27 expected, observed/expected ratio (o/e) 0.99, 90% interval 0.72 to 1.37.
Homologues: Orthologues: macaque PPP1R42 (98% identical), chimpanzee PPP1R42 (92% identical), rabbit PPP1R42 (90% identical), pig PPP1R42 (90% identical), dog PPP1R42 (89% identical), mouse Ppp1r42 (87% identical), rat Ppp1r42 (87% identical), tropical clawed frog ppp1r42 (64% identical), zebrafish ppp1r42 (58% identical), Drosophila melanogaster TbCMF46 (21% identical), Drosophila melanogaster Ppr-Y (19% identical). Paralogues in human: LRRC9 (26% identical), LRGUK (25% identical), DNAAF1 (23% identical), LRRCC1 (23% identical), LRRC49 (22% identical), DRC3 (21% identical), CEP97 (21% identical), LRRC43 (20% identical), DNAAF11 (20% identical), LRRC46 (17% identical), LRRC23 (16% identical), LRRC61 (15% identical), and 1 more.
Diseases named in the same sentence as PPP1R42 in open-access papers:
PPP1R42 is named in the same sentence as 1 disease in open-access papers, as found by Europe PMC text mining. Sharing a sentence is not in itself a finding about the gene and the disease. The quoted sentences say what the papers report.
cryptorchidism (1 paper, 2020). The failure of one or both testes of a male fetus to descend from the abdomen into the scrotum during the late part of pregnancy. "In addition, two homozygous SNPs in the PRICKLE3 and PPP1R42 genes are proposed to cause cryptorchidism in horses." (PMID 31936283, 2020).